ID1 (inhibitor of DNA binding 1)
Diseases named in the same sentence as ID1 in open-access papers (continued):
Sharing a sentence is not in itself a finding about the gene and the disease.
prostate carcinoma (continued). "Likewise, Fra-1 and ID1 have been proved to exert oncogenic function in breast and prostate cancers, whereas overexpression of these genes not only predict better survival in cancer patients, but also sensitized cancer cells to different chemotherapeutics." (PMID 24444035, 2014). "Furthermore, Id1 protein expression in prostate cancer cells mediated resistance to apoptosis induced by TNFα." (PMID 24378760, 2014). "Over-expression of Id-1 (inhibitor of differentiation/DNA synthesis) which belongs to the Id family of helix–loop–helix proteins is a key factor in promoting angiogenesis through activation of the VEGF in prostate cancer cells." (PMID 23308170, 2013). "Moreover, Id1 has been shown to mediate chemotherapy resistance in hormone-independent prostate cancer cells and ERK activation, and JNK and p38MAPK inhibition by Id1 in those cells has been suggested to be responsible for that resistance." (PMID 23311395, 2013). "Moreover, ID1 inhibits cell differentiation and promotes invasion in several types of malignant cancers, including breast and prostate cancers and non-small cell lung carcinoma." (PMID 24137437, 2013). "Despite significant advances in our understanding of the mechanism of action of Id1 in prostate cancer, such as regulation of p16, EGFR, androgen independence, prostate-specific antigen expression and its role in cell proliferation and metastasis, the expression Id1 has remained controversial." (PMID 23342268, 2012). "Aptamer or small molecule inhibitor that could target HLH domain of Id1 and Id3 could therefore be an ideal therapeutic approach in prostate cancer." (PMID 23342268, 2012). "It is possible that Id1 transcript is particularly sensitive in terms of how the sample is prepared, for example, the study demonstrating decreased Id1 in a membrane array also showed decreased expression of monocyte chemotactic protein-1 (MCP-1) in prostate cancer." (PMID 23342268, 2012). "A number of studies had shown that Id1 is a potential therapeutic target in prostate cancer." (PMID 23342268, 2012). "Our results suggest that increased Id1/Id3 could lead to downregulation of all three CDKNIs resulting in aggressive phenotype in prostate cancer." (PMID 23342268, 2012). "In other cases, prostate cancer cells can overexpress genes responsible for osteoclast differentiation and osteoblast mineralization, such as parathyroid hormone-related protein (PTHrP) and inhibitor of DNA binding-1 (Id-1)." (PMID 21603150, 2011). "To analyse whether downstream factors of Id-1 are responsible for its pro-osteolytic effect in prostate cancer cells, we used RT–PCR to test the expression of several secretory factors in prostate cancer cells expressing various levels of Id-1." (PMID 20010941, 2010). "In a recent study, overexpression of BMP-6 was shown to be correlated with increased Id-1 expression, suggesting that Id-1 might work downstream of BMP-6 in promoting prostate cancer progression." (PMID 20010941, 2010). "Overall, these results imply that Id-1 has a role in prostate cancer to bone metastasis." (PMID 20010941, 2010). "In prostate cancer, Id-1 has been shown to promote cancer progression through various mechanisms." (PMID 20010941, 2010). "We analysed whether the knockdown of Id-1 in prostate cancer cells would also affect their ability to mediate bone cell activities." (PMID 20010941, 2010). "As TNF-β only partially rescued the phenotypes induced by modulating Id-1 in prostate cancer cells, we speculated that secretory factors other than TNF-β might also be involved." (PMID 20010941, 2010). "Most importantly, Id-1 has been shown to promote metastasis of prostate cancer." (PMID 20010941, 2010). "We believe that combinatorial effects from all the Id-1 downstream factors could help to explain the mechanisms of Id-1-mediated prostate cancer-mediated osteoclast differentiation and osteoblast mineralisation." (PMID 20010941, 2010).
prostate carcinoma (continued). "Id-1 is overexpressed in and correlated with metastatic potential of prostate cancer." (PMID 20010941, 2010). "This study has identified a new role of Id-1 in prostate cancer to bone metastasis and piloted other studies to analyse whether Id-1 could be used as a prognostic marker and therapeutic target in prostate cancer to bone metastasis." (PMID 20010941, 2010). "Hence, increased sensitivity to taxol-mediated JNK activation and apoptosis in prostate cancer could be reached by using small RNA interfering technology to down-regulate Id1." (PMID 28122577, 2017). "Interestingly, it has been suggested that low levels of PSA and PSAP in aggressive prostate cancer might be due to Id1 overexpression." (PMID 28122577, 2017). "Increased Id1 and Id3 expression could therefore significantly decrease the expression of CDKNIs as shown in this and other studies that could be a mechanism leading to aggressive phenotype in prostate cancer." (PMID 23342268, 2012). "In addition, Id-1 also modulates prostate cancer-mediated osteoblast mineralisation." (PMID 20010941, 2010). "Id-1 promotes survival of prostate cancer cells through the NF-κB pathway, and it regulates the apoptotic response of cancer cells towards various chemodrugs, such that inactivation of Id-1 results in increased sensitivity of prostate cancer cells to paclitaxel through the JNK pathway." (PMID 20010941, 2010). "The expression of ID1 in some common cancer types, including HCC, breast invasive carcinoma, lung adenocarcinoma, and prostate cancer, is significantly lower in tumor samples than in normal samples." (PMID 37964494, 2024). "Mostly, Id1 is hazardous to the therapeutic resistance and prognosis of cancer, but in NSCLC, GBM and prostate cancer some shows that it is a sensitive marker to chemotherapy or radiotherapy." (PMID 32410828, 2020). "The expression of ID1, ID2, and at a lesser amount the ID3 genes were also investigated in several studies including prostate cancer researches and the relationship between their over-expression and cancer incidence was clearly perceived." (PMID 30876429, 2019). "In prostate cancer Bcl3 is overexpressed via IL6, leading to the up-regulation of Id1 and Id2, and inducing resistance against anticancer drugs." (PMID 28122577, 2017). "Semiquantitative analysis of Id1 and Id3 expression in prostate cancer specimens using nonparametric Kruskal–Wallis analysis essentially validated our observations stated above: increased Id1 and Id3 expression was significantly associated with increasing grade of prostate cancer." (PMID 23342268, 2012). "The prostate cancer cell lines LNCaP and DU145 expressed Id1 and Id3 as determined by Western blot analysis (Id1 and Id3 in LNCaP and DU145)." (PMID 23342268, 2012). "Id-1 was found to negatively regulate TNF-β and this correlation was confirmed in human prostate cancer specimens (P=0.03)." (PMID 20010941, 2010). "Thus, Id1/3-PA7 could have effects on androgen-independent proliferation of prostate cancer cells." (PMID 20842131, 2010). "Several ways to induce EMT in prostate cancer cells have been described, including overexpression of CAV1 and ID1 or MMP14 in LNCaP cells, EGF treatment of DU145 cells, depletion of PDEF or BMP7 treatment of PC3 cells." (PMID 18852876, 2008). "Also, TGF-β increased the expression of ID1 and ID3 in prostate cancer cell lines and so far, only lactoperoxidase was reported to decrease ID1 and ID3 expression on oral squamous oral epithelial cell line." (PMID 33477984, 2021). "In vitro studies have shown that inhibition of cell viability of prostate cancer cells by GT3 is the result of a multipronged effect that involves the activation of the JNK pathway and suppression of NF-κB via downregulation of EGFR and Id-1." (PMID 32414345, 2020).
prostate carcinoma (continued). "In mouse prostate model, overexpression of Id1 alone is not sufficient to drive neoplastic change 61, but Id1 is proved to regulate proliferation, apoptosis, and androgen-independence of prostate cancer (PCa) cell." (PMID 32410828, 2020). "A targeted network analysis of gene expression profiles in colorectal cancer cells revealed that ONC201 downregulates stem cell pathways such as Wnt signaling and modulates genes (ID1, ID2, ID3 and ALDH7A1) known to regulate self-renewal in colorectal, prostate cancer and glioblastoma." (PMID 28767654, 2017). "Id1 expression was also not observed in the stromal compartment in either normal prostate or prostate cancer." (PMID 23342268, 2012). "The decrease in proliferation in cells lacking both Id1 and Id3 is also not significantly different from cells lacking Id3 alone, further suggesting a dominant role of Id3 in prostate cancer cell proliferation." (PMID 23342268, 2012). "We found that TNF-β was responsible for Id-1-mediated inhibition of prostate cancer cell-mediated osteoblast mineralisation, but was not accountable for Id-1-mediated activation of prostate cancer cell-mediated osteoclast differentiation." (PMID 20010941, 2010). "In prostate cancer cells, the ability of Id-1 to modulate bone cell differentiation favouring metastatic bone disease is partially mediated by TNF-β, and Id-1 could be a potential therapeutic target for prostate cancer to bone metastasis." (PMID 20010941, 2010). "Id-1 promotes angiogenesis through upregulation of VEGF, while it also binds to caveolin-1 to induce epithelial–mesenchymal transition in prostate cancer cells." (PMID 20010941, 2010). "In vitro, breast and prostate cancer cells treated with halofuginone showed inhibition of BMP signaling demonstrated by inhibition of BMP-responsive promoter, inhibition of Phospho-Smad1/5/8 and reduction of ID1, a regulator of cancer cell growth and migration." (PMID 29156807, 2017). "However, TNF-β alone is not sufficient to explain all of the prostate cancer cell-mediated bone cell differentiation resulting from modulating Id-1 expression level." (PMID 20010941, 2010). "However, the medium derived from PC3-shId-1 is still incapable of inducing osteoblast mineralisation, suggesting that Id-1 might be sufficient to inhibit prostate cancer cell-mediated osteoblast mineralisation, but is not the sole regulator of this event." (PMID 20010941, 2010). "Because BMPs have very important roles in the development of bone metastasis in prostate cancer cells, it might be possible that BMP-2 in the bone environment promotes metastasis of cancer cells to bone through upregulation of the intrinsic expression of Id-1 in cancer cells." (PMID 20010941, 2010). "Besides the CDKN/pRb pathways, Id1/3-PA7 could interestingly be used to analyse EGFR pathway-dependent functions, as Id proteins, especially Id1, induce upregulation of EGFR in different tumour cells, very frequently in androgen-independent prostate cancer cells." (PMID 20842131, 2010).
hepatocellular carcinoma (32 papers, 2008 to 2025). A malignant tumor that arises from hepatocytes. "Consistent with this, PGC1α regulates glucose metabolism, including glycolysis and gluconeogenesis, and ID1-associated c-Myc-mediated aerobic glycolysis and glutaminolysis have been reported in hepatocellular carcinoma cells." (PMID 35897813, 2022). "It has reduced proliferation in hepatocellular carcinoma cells by suppressing ID-1 and inhibited invasion and metastasis in both in vitro and in vivo models." (PMID 41303564, 2025). "A role for ID1 in VM formation by TNBC (MDA‐MB‐231‐LM2 cells) and PDAC (BxPC‐3 and AsPC‐1) cancer cells was supported via ID1‐targeting siRNA knockdown; and concurs with a recent study by Zhang and colleagues on hepatocellular carcinoma cells." (PMID 40116596, 2025). "It has been shown that the downregulation of ID1 suppresses the malignant phenotype of hepatocellular carcinoma by inhibiting the β-catenin pathway." (PMID 39052126, 2024). "Knockdown of ID1 in oxaliplatin-resistant hepatocellular carcinoma (HCC) cells reduces proliferation and induces apoptosis." (PMID 31500396, 2019). "It has been shown that Id1 and c-Myc positively regulate each other’s expression in hepatocellular carcinoma cells and promote c-Myc-mediated glycolysis under aerobic conditions." (PMID 28122577, 2017). "Berberine, an isoquinoline alkaloid present in different herbs, including barberry, has shown anti-proliferative and anti-metastatic effects in hepatocellular carcinoma mice via Id1 down-regulation at the transcriptional level." (PMID 28122577, 2017). "The active compounds tetramethylpyrazine, which was extracted from a Chinese medicinal plant, and heparan sulfate mimetic WSS25 respectively inhibited angiogenesis and tumor growth of lung and hepatocellular cancer by blocking BMP/SMAD/Id-1 signaling." (PMID 27661009, 2016). "There is also emerging evidence for ID1 to mediate VM formation in hepatocellular carcinoma." (PMID 40116596, 2025). "ID1 is also reported to be involved in TGFβ1-induced EMT activation, thus enhancing tumor progression in human cancer cells; while inactivation of ID1 by inhibiting ID1 expression via berberine has potential therapeutic value against primary and metastatic growth of hepatocellular cancer." (PMID 28611292, 2017). "ID1 can stabilize HIF-1α protein in hepatocellular carcinoma cells." (PMID 27127787, 2016). "They found that BMP9-ID1 signaling promotes epithelial cell adhesion molecule(EpCAM)-positive cancer stem cells by activating Wnt/β-catenin signaling, which indicates that BMP9 and ID1 may be involved in the occurrence and development of hepatocellular carcinoma." (PMID 39619441, 2024). "As previously reported, ID1 induces c-Myc activation through the Wnt/β-catenin pathway, thereby promoting G6PD transcription, and then activating the pentose phosphate pathway, resulting in chemoresistance to oxaliplatin in hepatocellular carcinoma." (PMID 39052126, 2024). "Increased levels of Id1 have been also detected in tissue specimens from patients with cirrhosis without hepatocellular carcinoma and have been correlated with higher probability to develop the tumor." (PMID 28122577, 2017). "Id-1 suppression, however, has been found to down-regulate VEGF in hepatocellular carcinoma." (PMID 19014499, 2008). "Another study demonstrated that the ID1/Wnt/β-catenin signaling cascade regulates the attachment of c-Myc with the G6PD promoter and increases the transcription of G6PD, resulting in enhanced cell proliferation and drug resistance for oxaliplatin in hepatocellular carcinoma (HCC)." (PMID 38139067, 2023). "Likewise, we found that activin B and, to a lesser extent, activin A, induced HAMP mRNA in HepG2 hepatoma cells at 4 h posttreatment but did not significantly induce ID1 mRNA." (PMID 28893916, 2017).
glioblastoma (30 papers, 2013 to 2024). The most malignant astrocytic tumor (WHO grade IV). "This study, in addition to further research, can help clarify the mechanisms through which ID-1, as a passenger mutation, mediates chemoresistance in glioblastoma cells." (PMID 39455562, 2024). "If so, this finding would support our hypothesis that the metabolic phenotype seen in ID-1 expressing glioblastoma cells underlies treatment resistance in glioblastoma." (PMID 39455562, 2024). "We hypothesize that as a passenger mutation, ID-1 expression in glioblastoma cells promotes 1-C mediated purine synthesis, and thereby facilitates the maintenance of stem-like characteristics and proliferative capacity." (PMID 39455562, 2024). "Using a glioblastoma treatment resistance and disease recurrence model, we show that ID-1-mediated glioblastoma progression is accompanied by upregulation of 1-C mediated de novo purine synthesis and that the resulting metabolic phenotype underlies temozolomide resistance in glioblastoma." (PMID 39455562, 2024). "In our previous work, we identified a role for the epigenetic modifier ID-1 in temozolomide resistance in glioblastoma." (PMID 39455562, 2024). "Increased ID-1 expression in glioblastoma cells mediates chemoresistance and a quiescent stem-like state that allows these cells to initiate tumor recurrence." (PMID 39455562, 2024). "As deficits in 1-C metabolism would be predicted to result in the diminished availability of essential intermediates for purine synthesis, these data suggest that ID-1 KO glioblastoma cells harbor a metabolic phenotype characterized by purine deficiency." (PMID 39455562, 2024). "Till date, role of ID1 in preserving stemness and drug resistance is elucidated in hepatocellular CSCs glioblastoma CSCs and colon CSCs." (PMID 39123206, 2024). "We found that glioblastoma tumourigenesis in an ID-1 KO model of glioblastoma treatment resistance and disease recurrence is accompanied by upregulation of 1-C mediated de novo purine synthesis." (PMID 39455562, 2024). "We show that the accumulation of AICAR in glioblastoma cells is due to impairment of the mechanisms involved in the conversion of AICAR to AMP upon ID1 knockout, as evidenced by the reduction in ADSL expression in ID-1−/− cells." (PMID 39455562, 2024). "Previously, TGF-β signalling activity has been found to be upregulated in perivascular niches and closely associated with stemness markers such as Id1, CD44, Sox4 and Sox2, suggesting an underlying inherent plasticity of glioblastoma tumour cells." (PMID 39724753, 2024). "To determine if purine synthesis inhibition with ID-1 KO resulted in a functional phenotype in glioblastoma cells, we performed a cell proliferation assay in U251-ID-1-null and U251 parental cells." (PMID 39455562, 2024). "Here, we established that inhibitor of differentiation 1 (ID1)high/activin Ahigh glioblastoma cell confers resistance to BVZ." (PMID 38658527, 2024). "Supplementation with exogenous purines restores proliferation in ID-1-deficient cells, while inhibition of purine synthesis with AICAR sensitizes temozolomide-resistant glioblastoma cells to temozolomide chemotherapy." (PMID 39455562, 2024). "Further studies are required to elucidate the regulatory role of AMPK signaling in the metabolic reprogramming of ID-1-high glioblastoma cells." (PMID 39455562, 2024). "Inhibition of ID1 enhanced the effect of temozolomide in glioblastoma, implying that ID1 is a contributor to drug resistance." (PMID 37964494, 2024). "Prior reports show that STAT3 up-regulates ID1 expression by binding to the ID1 promoter in the glioblastoma." (PMID 37373188, 2023). "Inhibitor of differentiation 1 (ID1) is frequently overexpressed in glioblastoma cells, inhibits differentiation signals, and enhances MYC expression via activation of WNT and SHH signaling stemness." (PMID 35814409, 2022).